NANOG (Nanog homeobox)
Diseases named in the same sentence as NANOG in open-access papers (continued):
Sharing a sentence is not in itself a finding about the gene and the disease.
cancer (continued). "Thus, the absence of HMGCR (and NANOG) expression in the reprogrammed clones may reflect the incomplete or partial reprogramming usually observed in cell lines covering a wide range of human cancers, including BC." (PMID 38418798, 2024). "NANOG, another CSC marker and an inducer of CSCs properties in several cancers, has a higher expression in cancer stem cells compared to nonstem cancer cells." (PMID 37529165, 2023). "Organoids were also positive for multifunctional stem cell marker and cell-adhesion glycoprotein CD44, however they did not exhibit expression of other cancer stem cell markers such as OCT4, NANOG, SOX2, or ALDH1." (PMID 33732646, 2021). "We found that cancer cells overexpress epithelial-to-mesenchymal transition markers TWIST1 and SNAI2, as well as stem-like marker CD44 (but not CD133, SOX2 and/or NANOG)." (PMID 33531664, 2021). "NANOG and OCT3/4 mRNA expression levels were significantly downregulated while that of SOX2 was upregulated in cancer compared to noncancer tissues." (PMID 29849920, 2018). "The effect of the treatment was first evaluated by measuring the expression of stem cell transcription factors SOX2, NANOG, OCT4, SCA-1, and KLF4 for both cell cancer and non-CSC populations." (PMID 29868483, 2018). "Therefore, inhibition of NANOG might induce differentiation of CSCs into non-stem cancer cells." (PMID 27207017, 2016). "In cancer cell lines, CaMKIIγ was positively correlated with OCT4 and NANOG expression, but was not correlated with MYC or KLF4." (PMID 25965829, 2015). "Pluripotency factors OCT4 and NANOG, which play critical roles in POLR3G expression during early development, are notably omitted from the list of features that correlate with POLR3G levels in cancer, consistent with the absence of OCT4 and NANOG in most contexts." (PMID 37894362, 2023). "The nanog homeobox (NANOG) and the transforming growth factor (TGF)-β1/drosophila mothers against decapentaplegic protein (SMAD) signaling pathways are involved in several cancer stem cells but are not involved in PCSCs." (PMID 33336042, 2020). "Notably, D2 and NANOG are specifically expressed in CD34-negative cells (in the bulk of the tumor) and not in the cancer stem cell population." (PMID 32197405, 2020). "Cell morphology and p-MLC2 levels were assessed as amoeboid markers; ki-67 staining as a proliferative marker; WNT11, WNT5B and DAAM1 expression as non-canonical Wnt markers; and ALDH1A1, ALDH1A3, CD44, NANOG and OCT4 were evaluated as cancer stem cell-related markers." (PMID 33082334, 2020). "However, the proportion of NANOG protein expression that comes from NANOG1 and NANOG8 in cancer cells is not known." (PMID 26087476, 2015). "Furthermore, the expression of SOX2, but not OCT4 or NANOG, induced mammosphere formation in cultures, underscoring the possibility that increased expression of SOX2 is sufficient to induce cancer stem cell properties." (PMID 24355041, 2013). "One cancer stem cell marker SOX2 was up-regulated in HOS-R/DOXO compared to its parental line (log2 FoldChange 1.89, adjusted p value 6,45×10-04), while none of the cancer stem cell markers (SOX2, OCT4, SSEA4, NANOG and ABCG2) were modified in MTX-resistant lines." (PMID 31319571, 2019). "Furthermore, wiping out NANOG by TALEN or shRNA will not suffice to eradicate cancer." (PMID 29971070, 2018). "However, GTPBP2 ablation or overexpression could not affect the expression of NANOG and other stemness markers in CD133−CD44− and CD133−CD44+ cells, suggesting that GTPBP2 no longer regulates stemness in non-CCSC cancer cells probably due to altered intracellular microenvironment." (PMID 38468952, 2024).
cancer (continued). "However, the oncogenic transcription factor MYC also localizes to the POLR3G gene promoter in multiple cell lines and cancer contexts, presumably in the absence of OCT4 and NANOG, suggesting Pol III identity may be shaped by a distinct transcription factor repertoire in disease contexts." (PMID 37894362, 2023). "Notably, we could not detect substantial NANOG-GFP expression in either NANOG1- or NANOGP8-rescued cell lines using fluorescence microscopy, which suggests that excessive NANOG protein expression is lethal to somatic cancer cells, as speculated previously." (PMID 26087476, 2015).
tumor (528 papers, 2007 to 2026). "For example, CD24, which drives NANOG expression, has been identified as a liver cancer-causing gene with key features such as tumor initiation, self-renewal, chemoresistance, and differentiation." (PMID 40541178, 2025). "Higher NANOG expression, as indicated by values like 1.01E+11 and 7.27E+10, reflect a higher stemness potential, which is associated with more aggressive tumor behavior and possibly poorer prognosis." (PMID 40822502, 2025). "NANOG is a gene that controls stem-cell pluripotency, and has been implicated in tumor progression, metastatic potential, and poor prognosis in PDAC." (PMID 40699634, 2025). "The NANOG expression was increased across different tumor stages and grades, and was significantly associated with tumor invasion." (PMID 37627900, 2023). "Here, we showed that the cisplatin resistance of tumor cells is closely linked to secretory autophagy-mediated EGFR hyperactivation via the transcriptional induction of TRPV1 by NANOG." (PMID 37165076, 2023). "In vivo, repression of PCs activity by the general PC inhibitors α1-PDX, Spn4A, or decanoyl-RVKR-chloromethylketone (CMK) significantly reduced tumor expression levels of the stem cell markers LGR5 and NANOG that are associated with reduced tumor xenografts." (PMID 35267511, 2022). "We have also provided evidence that hypoxia-induced NANOG, a transcription factor associated with stem cell self-renewal, in tumor cells can directly bind to the TGF-β1 promoter to activate TGF-β1 expression." (PMID 33422072, 2021). "SOX2, OCT4, and NANOG are CSC markers associated with tumor proliferation and tumor differentiation." (PMID 34803458, 2021). "NANOG is another pluripotency-inducing transcription factor that has been linked to therapy resistance and tumor progression." (PMID 33420371, 2021). "Correlations with immune profiles CD4+, CD8+, and FOXP3+ tumor-infiltrating lymphocytes (TILs), tumoral PD-L1, and stem-related factors NANOG and SOX2 were assessed, and also associations with clinical data and patient survival." (PMID 33494389, 2021). "Previous studies demonstrate that NANOG is highly expressed in GC and significantly associated with tumor size and grade, along with decreased overall survival." (PMID 32626705, 2020). "Functionally, NANOG overexpression has been implicated in tumor transformation, tumorigenicity, metastasis, and is also correlated with poor differentiation status and chemoresistance." (PMID 32635524, 2020). "Quantitative realtime polymerase chain reaction (qRT-PCR) analysis showed that the expression levels of stemness-associated genes, including OCT4 and NANOG, and tumor markers, including AFP and CK19, in HCC cells were downregulated by ATO." (PMID 31186405, 2019). "In the assessment of the relationship between protein expression and tumor stage, strong and moderate expression of NANOG or MK displayed direct associations with late-stage tumors (stage III and IV; p = 0.047 and 0.048 for NANOG and MK, respectively)." (PMID 29113102, 2017). "Expression studies of OCT4, SOX2 and NANOG have also established a positive correlation with tumour grade, thus an association with poor prognosis." (PMID 26580604, 2015). "Our study aims to evaluate the expression of the markers CD133 and NANOG, associated with tumor stem cells, and to analyze their link with epidemiological and histological parameters, thus contributing to early diagnosis and the development of targeted therapies." (PMID 39459448, 2024).
tumor (continued). "In addition, among all genes associated to maintaining stemness feature of cells, NANOG has also been found in a variety of tumor types, including oral, kidney, liver, prostate, breast, ovarian, cervix, lung, stomach, brain, and prostate malignancies." (PMID 38846985, 2024). "Additionally, the plasticity of CSCs plays a significant role in promoting stemness, as evidenced by the overexpression of stemness-associated transcription factors (e.g., OCT3/4, SOX2, NANOG) among others, in diverse tumor types." (PMID 37784157, 2023). "Interestingly, we found that the NANOG signature was inversely associated with the T cell infiltration signature in multiple tumor types." (PMID 35104240, 2022). "Importantly, NANOG, a marker associated with tumor initiation capabilities was upregulated in MDA-FOXA1 cells." (PMID 33417085, 2021). "High NANOG expression is associated with poor tumor differentiation and advanced tumor stage." (PMID 33439550, 2021). "Notably, the inhibition of the NANOG signaling caused reversal of immune-resistant phenotypes of the tumor cells and led to long-term control of the disease." (PMID 31992715, 2020). "Importantly, patients with combined NANOG+/HSP90A+ level was strongly associated with large-sized tumor and chemo-radiation resistance than those with NANOG−/HSP90A− level." (PMID 31992715, 2020). "The upregulation of NANOG expression is linked to tumor progression and relapse." (PMID 29963272, 2018). "Similarly, overexpression of NANOG is associated with unfavorable tumor features and poor survival of OCSCC patients." (PMID 28321397, 2017). "Interestingly, the IHC co-expression pattern of NANOG and MK represented a stronger association with tumor histological grade, and strong co-detection of the two marker proteins was observed in high-grade OSCC." (PMID 29113102, 2017). "CXCR4+ cells presented CSC characteristics, such as increased resistance to tyrosine kinase inhibitors, higher sphere-forming ability, and tumor growth-inducing potential in vivo, and expressed high levels of stem cell-associated makers NANOG, OCT3/4, and SOX2." (PMID 27293448, 2016). "In the present study, by combining clinical sample analyses with in vitro experiments, we characterized a niche harboring quiescent stem-like tumor cells of the SOX2+ HIF-1α+ RNApII-S2P-/low or NANOG+ HIF-1α+ RNApII-S2P-/low phenotypes, which are associated with an enhanced tumorigenic capacity." (PMID 26799577, 2016). "Importantly, we have evidence that reduced MIR9-2 expression is associated with tumour progression and that the regulation of NANOG and MIR9-2 could be instrumental for developing therapies for the targeted treatment of TGCTs." (PMID 38693576, 2024). "Additionally, high NANOG expression was associated with advanced tumour grade (p < 0.001)." (PMID 36114703, 2022). "Consequently, it results in the demethylation of the multipotent factor NANOG's mRNA, and hypomethylation increases the stability of mRNA so as to causes high expression of NANOG, further inducing the maintenance and metastasis of tumor stem cells." (PMID 31001320, 2019). "A major limitation of the present study investigating OCT-4- and NANOG-mediated tumour progression in OSCC+OSMF is the small sample size." (PMID 41376750, 2025).
tumor (continued). "This study is especially important for CSC-marker research because it suggests that recurrence-specific tumor biology influences the prognostic implications of NANOG and SOX2." (PMID 40227667, 2025). "Several lines of evidence have suggested that the expression of OCT-4 and NANOG is closely related to tumorigenesis, distant recurrence, and tumour metastasis after treatment." (PMID 41376750, 2025). "NANOG positivity also aids in proper documentation of inherent potential of stemness of these metastatic tumor epithelial cells and so next level of lymph nodes should be thoroughly screened and treated." (PMID 40822502, 2025). "- Plasticity: Ability to shift differentiation states.- Pluripotency Markers: Expression of OCT4, SOX2, and NANOG.- Self-Renewal: Maintains tumor’s aggressive behavior and adaptability." (PMID 39857670, 2025). "As a key pluripotency factor, OCT4 works with SOX2 and NANOG to sustain an undifferentiated, stem-like state, preventing normal differentiation processes and driving tumor progression." (PMID 40722714, 2025). "It has been observed that NANOG expression increases in many tumours derived from various tissues, including breast, cervix, ovary, prostate, head and neck, kidney, lung, central nervous system, and gastrointestinal tract." (PMID 40729003, 2025). "These complex interactions between tumor progression, immune modulation, and systemic inflammation also explain the observed overexpression of NANOG in PDAC." (PMID 40699634, 2025). "Subsequently, overactivation of the EGFR-AKT signaling pathway confers resistance to T cell-mediated cytotoxicity in NANOG+ tumor cells." (PMID 39919692, 2025). "Within CSCs, NANOG promotes metastasis, self‐renewal, tumourigenesis, tumour recurrence and drug resistance." (PMID 40665579, 2025). "Cancer stem cells express pluripotency markers such as OCT4, SOX2, and NANOG, maintaining self-renewal and adaptability, which are critical for the aggressiveness of the tumor." (PMID 39857670, 2025). "Protein expression of ZFP36, LRP5, β-catenin and stemness factor NANOG in tumor samples was then analyzed." (PMID 40038255, 2025). "NANOG positivity indicates that these metastatic tumor epithelial cells had inherent potential of stemness." (PMID 40822502, 2025). "This variability underscores the heterogeneity of tumor cell populations within the lymph nodes and highlights the need for further investigation into the clinical implications of NANOG expression levels in OSCC metastasis." (PMID 40822502, 2025). "All the 15 nodes which were positive by RT-LAMP assay were subjected to Real Time PCR for detection of a progenitor cell marker, NANOG to predict potential stemness of these metastatic tumor cells." (PMID 40822502, 2025). "Our findings provide a notable contrast to the prevailing literature, which often associates high expression of pluripotency-associated transcription factors (NANOG and SOX2) with increased metastatic potential in tumor cells." (PMID 40227667, 2025). "The interplay between cellular plasticity and stemness factors like OCT4, SOX2, and NANOG enables PCa cells to adapt under therapeutic pressure, contributing to tumor heterogeneity, EMT activation, and drug resistance." (PMID 40722714, 2025). "Many molecules have been proposed as markers (ALDH1a1, ABCG2, CD44, CD133, CD271, NANOG), but they are also found in non-tumor stem cells and normal melanocytes." (PMID 40806546, 2025). "Experiments proved that down-regulating DNMT1 to reduce the methylation level of CpG in NANOG promoter can enhance the CSC capability of tumor cells, which is confirmed as an indicator of the conversion of non-CSCs to CSCs." (PMID 38561775, 2024). "We identified MIR182, MIR183, MIR371, MIR373, MIR512-1, MIR512-2, MIR515-1, and MIR520e exhibiting high expression and MIR216b, MIR887, MIR9-2, and MIR9-3 exhibiting low expression in NANOG H/L tumours." (PMID 38693576, 2024).